CASC8 (cancer susceptibility 8)
Diseases named in the same sentence as CASC8 in open-access papers (continued):
Sharing a sentence is not in itself a finding about the gene and the disease.
pancreatic adenocarcinoma (2 papers, 2020 to 2023). "The aim of this study was to explore the association between the expression of a long non-coding RNA (lncRNA), cancer susceptibility candidate 8 (CASC8), and pancreatic adenocarcinoma (PAAD)." (PMID 32582694, 2020). "CASC8 is located on chromosome 8q24, and its specific upregulation in pancreatic adenocarcinoma might indicate poor prognosis." (PMID 36871072, 2023). "CASC8 might be involved in epithelial mesenchymal transition (EMT) and pancreatic adenocarcinoma progression." (PMID 36871072, 2023).
tuberculosis (2 papers, 2020 to 2023). A chronic, recurrent infection caused by the bacterium Mycobacterium tuberculosis. "LncRNA CASC8 polymorphism was proved to be consistent with the trend of increased risk of tuberculosis, suggesting the biomarker potential of CASC8 for tuberculosis clinical progression." (PMID 37125193, 2023). "The aim of this study was to explore the associations between lncRNA CASC8 genetic polymorphism and tuberculosis risk." (PMID 32034808, 2020). "Our findings suggest that genetic polymorphisms of LncRNA CASC8 may play an important role in TB risk and inflammatory response and are expected to serve as a new target for diagnosing tuberculosis." (PMID 32034808, 2020). "Our results provide evidence that CASC8 may act as a biomarker for the progression of clinical tuberculosis." (PMID 32034808, 2020). "Thus, our study selected a set of SNPs within CASC8 among 900 tuberculosis cases and 1534 healthy controls in the Han Chinese population and systematically analyzed the associations between lncRNA polymorphisms and the occurrence and clinical characterization of TB infections." (PMID 32034808, 2020). "We investigated whether the dominant model of four candidate SNPs in CASC8 are related to the clinical manifestations of tuberculosis in TB patients with complete clinical data and the results of single SNP analysis." (PMID 32034808, 2020).
adenoma (1 paper, 2025). A neoplasm arising from the epithelium. "Interestingly, CASC8 polymorphisms have also been associated with differential cancer risks in adenomas and other cancer types." (PMID 40243746, 2025).
anxiety disorder (1 paper, 2024). A category of psychiatric disorders which are characterized by anxious feelings or fear often accompanied by physical symptoms associated with anxiety. "CASC8’s role in anxiety disorders is linked to its influence on neural development and function, with the haplotypic block rs4733767 indicating genetic susceptibility." (PMID 39165506, 2024). "Notably, entities such as CAMKMT, NCKAP5, CASC8, and rs56242606 exhibit positive associations with anxiety disorders." (PMID 39165506, 2024).
cervical carcinoma (1 paper, 2015). A carcinoma arising from either the exocervical squamous epithelium or the endocervical glandular epithelium. "PDCD6 gene expression was higher in cells sensitive to L-OHP, whileexpression of PDS5B, UBL3, MTIF3,XPO4, CASC8, and GTF3A was lower.UBL3 was identified as one of seven genes that predict relapse andsurvival in early-stage cervical carcinoma patients." (PMID 26678268, 2015).
non-alcoholic steatohepatitis (1 paper, 2019). "First, there are high levels of heterogeneity in HCC-related clinical indices, such as alcoholic and non-alcoholic steatohepatitis within the case group, presumably leading to distinct results concerning the association between CCAT2 and CASC8 gene variations and hepatic tumorigenesis." (PMID 31398859, 2019).
pancreatic neuroendocrine tumor (1 paper, 2020). Pancreatic endocrine tumor, also known as pancreatic neuroendocrine tumor (PNET), describes a group of endocrine tumors originating in the pancreas that are usually indolent and benign, but may have the potential to be malignant. "The expression of CASC8 was observed to be high in 178 PAAD samples [fold change = 8.71, P = 0.0014, false discovery rate (FDR) = 0.04] and was related with poor prognosis, but not in pancreatic neuroendocrine tumor (pNET)." (PMID 32582694, 2020).
cancer (35 papers, 2015 to 2025). A tumor composed of atypical neoplastic, often pleomorphic cells that invade other tissues. "CASC8, located in the 8q24 chromosomal region, has also been studied for its association with cancer susceptibility, particularly in CRC." (PMID 40243746, 2025). "Long non-coding RNAs (lncRNAs) such as GAS5 and CASC8 have been implicated in cancer susceptibility." (PMID 40243746, 2025). "Several studies indicate that CASC8 can influence the proliferation, invasion, and metastasis abilities of cancer cells and is also associated with patient prognosis and treatment response in lung cancer and esophageal cancer." (PMID 39865281, 2025). "Studies have shown that ALKBH5-mediated demethylation of m6A leads to the overexpression of cancer susceptibility candidate 8 (CASC8) in ESCC and that CASC8 upregulation predicts poor prognosis in ESCC patients." (PMID 40356985, 2025). "The Cancer Susceptibility Candidate 8 (CASC8) is located at 8q24.21 and shows a substantial copy number amplification in cancer tissues." (PMID 36672865, 2023). "In the course of a preliminary analysis of the available bioinformatic data from TCGA (The Cancer Genome Atlas), we found a miserably studied lncRNA CASC8 (aka “Cancer Susceptibility Candidate 8”)." (PMID 36038677, 2022). "As the champion with the highest coefficient value among all member lncRNAs, the association between CASC8 and the malignant tumor has been marked recently." (PMID 36186449, 2022). "CASC8-rs1562430, in high LD (r2 > 0.85) with 18 CASC8 prioritized variants, has been previously associated with other cancers (breast, colorectal, and stomach)." (PMID 33517887, 2021). "It has been shown that CASC8, cancer susceptibility candidate 8, has been shown to be a tumor susceptibility gene." (PMID 34854360, 2021). "The lncRNA CASC8 is a susceptibility factor for cancer, but its specific role in NSCLC is not well understood." (PMID 33391435, 2021). "The lncRNA cancer susceptibility candidate 8 (CASC8) has been shown to be a tumor susceptibility gene 18, but its mechanism of action is not clear." (PMID 33391435, 2021). "The strongest risk effect was found for the novel intronic variant rs16902147 in the CASC8 (cancer susceptibility candidate 8) gene at 8q24 with an OR of 1.86 (95% CI 1.56–2.23; padj = 3.53 × 10−8) and EAF of 0.07." (PMID 34012061, 2021). "The gene polymorphisms of CASC8 have been reported to be closely related to the risk and progression of different cancers." (PMID 34199840, 2021). "Cancer susceptibility candidate 8 (CASC8 or CARLo-1) is located on 8q24 chromosome, in which MYC and several other lncRNAs are also located." (PMID 32582694, 2020). "Our findings suggest that there are different mechanisms underlying the CASC8 function between these cancers, and further functional experiments should be performed." (PMID 32582694, 2020). "Among long non-coding RNAs (lncRNAs) located in the chromosome 8q24 loci and involved in the carcinogenesis are colon cancer associated transcript 2 (CCAT2) and cancer susceptibility candidate 8 (CASC8)." (PMID 31398859, 2019). "Meanwhile, positive associations (although not strong to reach the genome-wide significance threshold level) were also found between CASC8 (cancer susceptibility candidate 8) and TA." (PMID 29445242, 2018). "Cancer susceptibility candidate 8 (CASC8) gene, a long non-coding RNA, is located in the region of 8q24, which is a gene desert region with no ability of protein coding." (PMID 27249003, 2016). "The HaploReg tool identified two correlated SNPs (rs9643226 and rs1447296) in high LD with the index SNP, rs1447295, located in the putative promoter region of the long non-coding RNA (lncRNA), CASC8 (cancer susceptibility candidate 8)." (PMID 25658610, 2015). "In addition to GAS5 and CASC8, other lncRNAs have been implicated in cancer development and progression." (PMID 40243746, 2025). "Studies have shown that cancer susceptibility candidate 8 (CASC8) is a tumor susceptibility gene." (PMID 38555384, 2024).
cancer (continued). "CASC8 polymorphisms (rs1447295 and rs10505477) are also risk factors for other types of cancer." (PMID 36672865, 2023). "Moreover, CASC8 polymorphisms (rs1447295 and rs10505477) have been reported as risk factors for some cancer types, such as gastric, hepatic, and breast cancers." (PMID 32582694, 2020). "CASC8 gene polymorphisms play important roles in different cancers." (PMID 32875717, 2020). "Cancer susceptibility candidate 8 (CASC8) is another lncRNA identified within the 8q24 gene desert." (PMID 31398859, 2019). "Positive association was also found between intronic variants in the cancer susceptibility 8 (CASC8) gene on chromosome 8q24 and TA for SNP rs10505477 genotypes and alleles (P = 8.16 × 10−5 and P = 1.7 × 10−5, respectively) and rs7014346 (P = 0.0005 for genotype under a recessive model)." (PMID 29445242, 2018). "Previous studies have reported that CASC8 is upregulated and promotes progression in various cancers." (PMID 39865281, 2025). "We downloaded expression data from The Cancer Genome Atlas (TCGA) database and analyzed CASC8 expression in 535 cancer tissues and 59 adjacent normal tissues." (PMID 33391435, 2021). "Based on the information available in four cancer databases (starBase, cBioPortal, circlncRNAnet, and UCSC Xena), we analyzed the CASC8 expression and its mutations, and the effect of this lncRNA on the survival in PAAD." (PMID 32582694, 2020). "Based on data for 178 cancer and four normal samples present in TCGA, the expression of CASC8 was found to be significantly upregulated in PAAD [FPKM, fold change = 8.71, P = 0.0014, false discovery rate (FDR) = 0.04]." (PMID 32582694, 2020). "Overall, in all the samples, the expression level of CASC8 in cancer tissues was 1.76-fold relative to that in normal tissues (1.46 vs. 0.83, P = 0.4369)." (PMID 32582694, 2020). "The expression of CASC8 in other six tumor samples was low, and four samples among these were moderately differentiated, one sample was highly differentiated, and its cancer stage was 1A(T1b)." (PMID 32582694, 2020). "In recent years, the clinical significance of CASC8 has been extensively studied, especially in cancer." (PMID 32582694, 2020). "In addition, CASC8 dysregulation was present in numerous cancers, including CRC, prostate cancer, and gastric cancer." (PMID 40243746, 2025). "CASC8 is an important factor in promoting the proliferation and chemoresistance of cancer cells." (PMID 36829596, 2023). "Additionally, rs10505477 disrupts the relationship between CASC8 and the POU5F1BB promoter, which is a cancer susceptibility gene." (PMID 36672865, 2023). "Cancer susceptibility candidate 8 (CASC8) is an lncRNA with no protein‐coding potential that is located in the 8q24 region." (PMID 32875717, 2020). "The rs10505477 may disrupt the correlation between CASC8 and the promoter of POU5F1BB, which was found to be a putative cancer susceptibility gene." (PMID 32582694, 2020). "High CASC8 expression correlated with a poor prognosis for patients with PDAC and contributed to cancer progression in vitro and in vivo." (PMID 39865281, 2025). "Total RNA-seq showed upregulation of 12 putative cancer-related genes near ISs, including MAGI1-AS1, HAS3, CASC8, BIRC2, and MMP12." (PMID 41157614, 2025). "CASC8 was lowly expressed in 2 tumor tissues, 1 sample was moderately differentiated (cancer stage III [T2N2]) and 1 sample was poorly differentiated (cancer stage IB [T2N0])." (PMID 37713870, 2023). "CCAT1::CASC8 was only recently reported in the fusion catalog generated by DEEPEST fusion, and VCL::ADK was only previously reported in a study of cancer cell lines." (PMID 37323575, 2023). "However, most of the published studies on CASC8 were made from analytical point of view and were devoted to establishing the correlation of individual nucleotide polymorphic substitutions (SNP) in its gene with the risks of development of various types of cancer." (PMID 36038677, 2022).
cancer (continued). "Both the levels of CASC8 and the levels of FOXM1 were higher in the cancer tissues than in the adjacent normal tissues." (PMID 33391435, 2021). "Cancer development was observed by the modulation of genes involved in cell death (HIST1H1T, CASP14, and DNAJC3), cancer related genes (WNT8A and CASC8), gene expression (transcription) (ZNF570 and ZFP42), and metabolism of proteins (CALB2 and KLHDC3)." (PMID 31797963, 2019). "Due to our small sample size, we did not analyze the relationship between cancer grade and stage and CASC8 expression." (PMID 37713870, 2023). "In addition, after exposure to TiO2 MPs, DEG related to cancer, cell death, and gene transcription were observed like WNT8A and CASC8 which are highly correlated with CRC development and progression." (PMID 31797963, 2019). "Most of the alterations of CASC8 in the PAAD samples were gene amplifications, which have not yet been fully studied in cancer." (PMID 32582694, 2020).
tumor (18 papers, 2016 to 2025). "To validate the expression level of CASC8 in tumor cells, we obtained a single-cell RNA sequencing dataset (scRNA-seq; CRA001160)." (PMID 39865281, 2025). "Fluorescence in situ hybridization (FISH) analysis of PDAC samples further corroborated these findings, revealing significantly higher CASC8 expression in tumor cells compared to normal cells." (PMID 39865281, 2025). "Five mice inoculated with sh-CASC8 + c-Myc cells exhibited significantly increased tumor volume and weight compared to the sh-CASC8 group upon BAY-876 injection." (PMID 39865281, 2025). "CASC8 plays a role in tumor progression by interacting with chromatin-modifying complexes and transcription factors." (PMID 40243746, 2025). "Cells with CASC8 knockdown and overexpression were subjected to cell viability, EdU, transwell assays, and used to establish subcutaneous and orthotopic tumor models." (PMID 39865281, 2025). "Our study identified c-Myc as a downstream target gene of CASC8, and genetic suppression of c-Myc exhibited tumor-suppressive effects in PDAC cells overexpressing CASC8." (PMID 39865281, 2025). "By cox regression analysis, we constructed the lncRNAs signature associated with genomic instability, including potential risk prognostic lncRNAs CASC8, AC015660.1 and AC104695.4, and tumor-suppressive lncRNAs LYPLAL1-AS1, AC069120.1, AC132938.2." (PMID 37713870, 2023). "The results showed that the expression level of CASC8 in tumor tissues was significantly higher than that in adjacent normal tissues (P = .0402), while the expression of LYPLAL1-AS1 showed an opposite pattern (P = .0143)." (PMID 37713870, 2023). "We also found that elevated expression of TM4SF1-AS1, CASC8, UCA1, and LINC00941 was associated with C1, C2, and C6, suggesting a tumor-promoting effect and poor prognosis." (PMID 36871072, 2023). "The expression of CASC8 was significantly increased in tumor tissues (P < .001), and the expression of LYPLAL1-AS1 was significantly higher in normal tissues (P < .001), indicating that LYPLAL1-AS1 is a protective gene." (PMID 37713870, 2023). "The expression of CASC8 was significantly higher in NSCLC tissues than in normal tissues adjacent to the tumor (P < 0.0001)." (PMID 33391435, 2021). "Notably, treatment with 3 mg/kg of BAY-876, a GLUT1 inhibitor that mimics glucose starvation, produced similar anti-tumor effects, suggesting a potential link between CASC8 and glucose metabolism in vivo (P < 0.001)." (PMID 39865281, 2025). "The functions of lncRNA CASC8 in normal tissues and developmental growth remain unclear, and current research primarily focuses on its regulatory role in tumor progression, its potential as a biomarker, and its candidacy as a therapeutic target." (PMID 39865281, 2025). "This analysis demonstrated that CASC8 expression was predominantly localized to tumor cells." (PMID 39865281, 2025). "Furthermore, consistent with the results in cell lines, we found that Z97832.2 and PAN3-AS1 expressed lowly in PAAD tumour tissues than those in adjacent normal tissues, but CASC8 and AC015660.1 showed the higher levels in tumour tissues." (PMID 36384673, 2022). "In addition, the higher expression of CASC8 and AC015660.1 prominently associated with the larger tumour size, and the more advanced grade and T-stage." (PMID 36384673, 2022). "Second, probably, rs10505477 allele could alter the interactions between the CASC8 and its cognate gene POU5F1B (POU class 5 homeobox 1 pseudogene 1), an acknowledged tumor susceptibility gene, by regulating the binding of some transcription factors to promoter of POU5F1B gene." (PMID 27249003, 2016). "Meanwhile, we noticed that CASC15, CASC8, CASC9, and CASC19 were highly expressed in tumor samples and CASC16 and CASC18 were lowly expressed in tumor tissues." (PMID 40746360, 2025).
tumor (continued). "Analysis initiated by fusions in the COSMIC-enriched cluster highlighted several putative or less appreciated oncogenic fusions, including CCAT1::CASC8 and VCL::ADK, based on their feature similarity to other well-known tumor-enriched fusions." (PMID 37323575, 2023). "Next, we examined the levels of CASC8, AC015660.1, Z97832.2 and PAN3-AS1 in HPDE6-C7 cell line, various PAAD cell lines and tumour and adjacent tissues of PAAD." (PMID 36384673, 2022). "We detected that the higher expression of CASC8 and AC015660.1 prominently correlated to the larger tumour size, and the more advanced grades and T-stages." (PMID 36384673, 2022). "The expression levels of CASC8 and AC015660.1 were significantly higher in PAAD cell lines and tumor tissues especially in patients with advanced grades and T-stages, while Z97832.2 and PAN3-AS1 were inverse." (PMID 36384673, 2022). "Here, we, for the first time, establish an ARRSM based on CASC8, AC015660.1, Z97832.2 and PAN3-AS1, which not only offer more promising targets, but also better assess tumour vascularization status and prognosis for PAAD patients." (PMID 36384673, 2022). "Compared with the adjacent normal tissues, CASC8 and AC015660.1 expressed higher in PAAD tumor tissues with more advanced grades and T-stages, however, Z97832.2 and PAN3-AS1 dropped." (PMID 36384673, 2022). "Moreover, CASC8 decreased the cisplatin sensitivity of ESCC cells and promoted ESCC tumor growth in vivo." (PMID 35982900, 2022). "The CASC8 locus is amplified in 5% of PC and codes for a non-protein coding RNA overexpressed in tumor vs. normal pancreatic tissue (Log2FC = 1.25, p value = 2.29 × 10−56)." (PMID 33517887, 2021). "Additionally, we verified the clinical significance of the four sARLNRs and found that the expression levels of CASC8 and AC015660.1 were significantly higher in PAAD cell lines and tumor tissues especially in patients with advanced grades and T-stages, while Z97832.2 and PAN3-AS1 were inverse." (PMID 36384673, 2022).
CASC8 also shares sentences with these, for which no sentence is quoted: esophageal cancer (3 papers); hepatocellular carcinoma (3); lung adenocarcinoma (2); acute myeloid leukemia (1); chronic heart failure (1); chronic pancreatitis (1); liver cancer (1); lymph node metastasis (1); osteosarcoma (1); rectal cancer (1); stomach cancers (1); thyroid cancer (1); tooth agenesis (1); type 2 diabetes mellitus (1).